INS (insulin)
Diseases named in the same sentence as INS in open-access papers (continued):
Sharing a sentence is not in itself a finding about the gene and the disease.
diabetes (continued). "However, a remark must be made on the absence of differentiation between controlled and uncontrolled diabetes, based on fasting glucose levels above 180 mg/dL, HbA1C over 9%, or increased insulin dose needs, creating a potential confounder for this risk factor." (PMID 39597838, 2024). "Moreover, the HOMA index can provide insights into insulin sensitivity and beta-cell function in both diabetic and non-diabetic individuals, thereby aiding in the identification of those at risk of developing diabetes." (PMID 39578883, 2024). "However, if hyperinsulinism was simply a consequence of beta-cell apoptosis, the increased insulin release should be short-lived, and those individuals most severely affected by HH would be expected to progress most rapidly to a state of insulin-deficient diabetes." (PMID 38279270, 2024). "Diabetes mellitus (DM) is a chronic metabolic disorder characterised by elevated blood glucose concentration due to insulin resistance, deficiency of insulin, or both." (PMID 38362147, 2024). "The mechanism underlying depression in patients with diabetes is still under investigation; however, it may partly be explained by the development of insulin resistance in the brain, caused by a failure of neurons to respond normally to insulin." (PMID 39409133, 2024). "In addition, ferritin may interact with serum adiponectin, an insulin-sensitizing adipokine, in modulation of the risk of diabetes." (PMID 38840960, 2024). "The objective of the present systematic review was to compare the incidence of falls in older adults with and without T2DM, as well as to verify whether older adults with diabetes on insulin or with polyneuropathy have a higher risk of falls than older adults without diabetes." (PMID 38413865, 2024). "Diabetes mellitus (DM), one of the most frequent metabolic disorders worldwide, is attributed to hyperglycemia caused by either reduced insulin emission or insulin resistance." (PMID 39725830, 2024). "Diabetes mellitus (DM) is a common group of metabolic disorders characterized by hyperglycemia due to the absolute or relative deficiencies of insulin action." (PMID 39769381, 2024). "In conclusion, diabetes caused by the heterozygous pathogenic variant R46Q in the insulin gene may be well treated on noninsulin regimens, in particular with agents that reduce the demand for endogenous insulin secretion." (PMID 39027635, 2024). "Although insulin is associated with weight gain and the risk of hypoglycemia, it should not be withheld from patients who cannot meet their glucose goals using other agents, and insulin should be used in any patient exhibiting symptoms of uncontrolled diabetes." (PMID 39835266, 2024). "Finally, we adjusted for several important confounding factors related to CVD risk, including age, menopausal age, insulin use, BMI, hypertension, diabetes mellitus, dyslipidemia, high alcohol intake, smoking, exercise, oral contraceptive use, and hormonal therapy use." (PMID 38613076, 2024). "Pancreatogenic diabetes also known as type 3c diabetes mellitus (DM) includes both structural and functional loss of glucose-regulating hormone (insulin) secretion in the context of exocrine pancreatic dysfunction." (PMID 39744270, 2024). "The association between diabetes distress remained statistically significant (β = −0.298, p = 0.004) after controlling for covariates (age, sex at birth, race, sleep apnea risk, T1D duration, and continuous subcutaneous insulin infusion) accounting for 20.9% of the variance." (PMID 39728281, 2024). "Similarly, acute myocardial infarction (AMI) secondary to advanced diabetes may seem spuriously linked to insulin use, as insulin is often prescribed at later stages of diabetes when the risk of AMI is already higher." (PMID 40979381, 2024).
diabetes (continued). "These diets may induce hyperglycemia, which is associated with increased pro-inflammatory cytokines, including IL-6 and TNF-α, leading to insulin resistance by disruptions in insulin signalling and subsequently might increase the risk of the diabetes complications." (PMID 38264289, 2023). "Hepatic insulin clearance is (at least partly) a heritable trait; several genetic variants that are involved in regulating insulin clearance have been identified in Mexican Americans, an ethnic group with a high prevalence of the metabolic syndrome and diabetes." (PMID 36901984, 2023). "Diabetes mellitus (DM) is a chronic metabolic disorder characterized by hyperglycemia caused by a defect in the secretion or action or both of insulin." (PMID 38022061, 2023). "Diabetes mellitus (DM) is familiar, associated with genetic and environmental factors, and is caused by insulin deficiency or decreased tissue and cell insulin sensitivity." (PMID 37504259, 2023). "Diabetes mellitus (DM) is characterized by an inability to regulate blood glucose in humans or animals due to either a deficiency of insulin or an erratic signaling pathway." (PMID 36840070, 2023). "A recent nested case-control study in the Framingham Offspring Study found that plasma BCAA levels are associated with fasting insulin levels and may predict future risk of diabetes, particularly in obese individuals and those with elevated fasting glucose levels." (PMID 37980456, 2023). "In diabetes mellitus (DM), insulin secretion or action is impaired, causing blood sugar levels to rise." (PMID 37779785, 2023). "Moreover, due to its ability to inhibit insulin secretion, leptin could serve as an adjunctive treatment for individuals with insulin-deficient diabetes under specific conditions." (PMID 38138996, 2023). "Type 1 diabetes (T1 DM) is caused by an absolute deficiency of insulin secretion owing to an autoimmune pathologic process occurring in the pancreatic islets." (PMID 37090383, 2023). "In 2021, the World Health Organization (WHO) raised the priority given to the prevention, control, and management of diabetes as well as its risk factors with the aim of expediting the necessary actions for diabetes management moving forward, 100 years after the discovery of insulin." (PMID 36673874, 2023). "Diabetes mellitus (DM) is defined as a metabolic disorder caused by less insulin secretion or impaired insulin action." (PMID 37091893, 2023). "Diabetes mellitus (DM) is a chronic disease caused by relative or absolute decreases in insulin secretion, resulting in metabolic disorders of carbohydrates, lipids, and proteins, especially an increase in blood glucose." (PMID 38201855, 2023). "Diabetes mellitus is a series of physiological dysfunctions characterized by hyperglycemia associated with abnormalities in carbohydrate, fat, and protein metabolism caused by resistance to insulin action, inadequate insulin secretion, or excessive glucagon production." (PMID 36770960, 2023). "Diabetes mellitus (DM) is a metabolic disease that results in hyperglycemia and is caused by either the low level of insulin in the body or resistance to insulin." (PMID 36976722, 2023). "Thus, two patients with heterozygous INS variants in our cohort had remission of diabetes." (PMID 36398453, 2023). "Diabetes mellitus (DM) is a systemic and chronic degenerative disease characterized by chronic hyperglycemia due to deficiency in the production or action of insulin, affecting the metabolism of carbohydrates, proteins, and fats." (PMID 36512089, 2023). "A clustering of concomitant diseases and risk factors likely may also contribute to this increased risk in diabetic patients on insulin and insulin use is likely to be a proxy for difficult glycemic control and/or longer duration of diabetes in patients with atrial fibrillation." (PMID 35976428, 2023).
diabetes (continued). "Diabetes mellitus (DM) is a chronic multi-system disease associated with either abnormality of insulin production in the pancreas, incapability of insulin utilization or both (American Diabetes Association [ADA] 2020)." (PMID 36625086, 2023). "Consequently, the high circulating glucose levels induce an increase in insulin production from the pancreas in fed and fasting states, which may cause type 2 diabetes mellitus." (PMID 37512149, 2023). "Furthermore, the exploration of the structural changes in insulin, resulting from genetic mutations, and the molecular biology involved can supply crucial information for the development of novel and improved insulin analogues used to treat diabetes." (PMID 37048081, 2023). "Diabetes mellitus is characterized by a disorder that results in the inability of the pancreatic islets to secrete insulin and/or the deficient action of insulin in the tissues, being classified as insulin-dependent or type 1 diabetes, or non-insulin-dependent or type 2 diabetes." (PMID 36830471, 2023). "Diabetes mellitus (DM) is defined as a chronic metabolic disorder of multiple aetiology which is characterized by hyperglycaemia caused by inadequate insulin secretion, insulin action or both." (PMID 37240914, 2023). "Diabetes mellitus (DM) is a chronic metabolic disorder, which is characterized by a deficiency of insulin secretion by the pancreas and or insulin resistance in peripheral tissues." (PMID 36825257, 2023). "It has also been recognized that diabetes and its complications are associated with a series of changes in endothelial dysfunction caused by several factors including an excess of plasma FFAs, alterations in glucose metabolism, impaired insulin signaling, chronic inflammation, and oxidative stress." (PMID 38025709, 2023). "Insulin treatment remained consistently associated with poor outcomes after adjustment for established confounders, with an adjusted hazard ratio of 3.11; (95% CI, 1.45–6.87; P = 0.009) in the overall cohort and 2.16 (95% CI, 1.08–4.59; P = 0.030) in the diabetes cohort." (PMID 37542280, 2023). "Similarly, genes ABCB11 (chromosome 2), ADCY5 (chromosome 3), CDKAL1 (chromosome 6), ANK1 (chromosome 8), GLIS3 (chromosome 9), and HKDC1 (chromosome 10) have been linked to various aspects of diabetes, including insulin release, glucose levels, β-cell function, and insulin resistance." (PMID 38274506, 2023). "Diabetes mellitus (DM) is a metabolic disorder syndrome caused by the absolute or relative insufficiency of insulin secretion and the decrease of insulin sensitivity of the corresponding target tissues." (PMID 37000070, 2023). "Primary hypoadrenalism (Addison’s Disease) is associated with Type 1 diabetes and may present in these patients with new-onset hypoglycaemia and decreasing insulin requirements, particularly in long-standing diabetes due to loss of the counter-regulatory hormones, glucagon and noradrenaline." (PMID 37892096, 2023). "Diabetes-associated pain hypersensitivity and allodynia have been observed in states of hyperglycemia—where mostly a situation of prolonged chronic inflammation has to be considered, and in situations of hypoglycemia, often as a result of excessive insulin therapy." (PMID 37069517, 2023). "Diabetes mellitus (DM) is a chronic, lifelong progressive metabolic disorder caused by impaired insulin secretion or insulin resistance, resulting in chronic hyperglycemia." (PMID 36900596, 2023). "We hypothesized that type 1 diabetes patients receiving this current standard of care and carrying a copy of the protective INS variant have a further reduced risk of developing diabetes complications compared to patients only carrying the susceptible INS variant." (PMID 36701305, 2023).
diabetes (continued). "Diabetes mellitus is a series of metabolic disorder syndromes, including protein, fat, and electrolytes, caused by the absolute or relative insufficient secretion of insulin and the decreased sensitivity of target tissue cells to insulin, with hyperglycemia as the main sign." (PMID 37039840, 2023). "Diabetes is the most common heterogeneous metabolic disorder, which is associated with disorders of glucose, lipid, and protein metabolism, characterized by elevated blood glucose or insulin response to tissue, which can lead to many complications, including diabetic skin wounds or ulcers." (PMID 36978721, 2023). "Diabetes mellitus is a metabolic disorder caused by either the total destruction of the pancreatic beta cells that secrete insulin for the uptake of glucose from the circulation or as a result of the inability of body cells to respond to the presence of insulin in the blood." (PMID 36837910, 2023). "Finally, and rather interestingly, liraglutide as an adjunct to insulin has been shown to improve glycaemic control, induce body weight loss and decrease exogenous insulin requirements and severe hypoglycaemia in patients with type 1 diabetes mellitus." (PMID 37209215, 2023). "Furthermore, physical exercise has not only been reported to raise glycemic control, but also to improve a patients insulin sensitivity and to repair some of the damage caused by diabetes-associated complications, such as impaired cardiovascular health, one of the most common complications." (PMID 36952453, 2023). "Furthermore, they stated that the expression of miR-146a in individuals susceptible to diabetes, patients with T2D tolerating insulin therapy, high obesity/glycemia, and T2D patients with diabetic foot ulcers and nephropathy was reduced in serum but was not linked with cell functionality." (PMID 36911496, 2023). "Activation of the BDNF/TrkB/CREB reduces hepatic gluconeogenesis, induces hepatic insulin signal transduction, and protects against pancreatic beta-cell loss in diabetes mellitus (DM)." (PMID 36787304, 2023). "However, insulin injection itself can cause distress to patients with diabetes." (PMID 37474582, 2023). "Diabetes Mellitus (DM) is a metabolic disorder caused by low insulin production or function, resulting in chronic hyperglycemia." (PMID 37845651, 2023). "Diabetes mellitus (DM) is a metabolic disease characterized by chronic hyperglycemia, as well as glucose, adipose tissue, and protein metabolism disorders caused by impaired insulin production by pancreatic β-cells and/or insulin resistance by peripheral tissues." (PMID 35237941, 2023). "In addition, a more complex polygenetic understanding of diabetes can be devised for each individual through a network of genes/variants involved in beta cell function and insulin mechanisms of action, which can be integrated with medical data to determine a patient’s diabetes risk score." (PMID 36830626, 2023). "Type-1 diabetes mellitus (DM) is the most common endocrine disorder that results from a deficiency of insulin, mainly due to autoimmune destruction of the pancreatic beta-cells." (PMID 36986192, 2023). "Patients with Diabetes Mellitus (DM) have been reported to have higher fall risk; the increased risk of falling due to DM was much more pronounced in insulin-treated patients compared to non- insulin-treated patients." (PMID 37685432, 2023). "Diabetes mellitus (DM) is a significant public health problem caused by unstable insulin secretion and/or insulin resistance, impairing carbohydrate, protein, and fat metabolism." (PMID 37372128, 2023). "Given that the surgical stress response may contribute to severe endocrinal disruption characterised by elevated cortisol and blood sugar levels as well as insulin resistance, this may place individuals with pre-operative diabetes mellitus at an even greater risk of POCD." (PMID 36836145, 2023).
diabetes (continued). "Furthermore, as in the case of diabetes, limiting the intake of any plant-based drink, which can cause large fluctuations in blood sugar and insulin (rice in particular), could be beneficial." (PMID 37048365, 2023). "Diabetes Mellitus (DM) is categorized as one of the frequently occurring disease worldwide, in which chronic hyperglycemia occurs due to insufficient production of insulin that causes metabolic disturbances of carbohydrate, lipid and protein." (PMID 36653816, 2023). "In addition, diabetes is associated with the accumulation of AGEs and patients with type 2 diabetes mellitus experience an increased risk to develop PD, indicating a possible insulin-modulating role in this latter condition." (PMID 37305556, 2023). "Diabetes Mellitus (DM) is a heterogeneous group of metabolic disorders characterized by chronic hyperglycemia that arises from defects in insulin secretion, insulin action, or both." (PMID 38269284, 2023). "Diabetes mellitus (DM) is a metabolic disorder characterized by chronic hyperglycemia (persistent elevation of blood glucose concentration) linked to a deficiency in either insulin secretion, insulin action, or a combination of these factors which resulted in high blood sugar levels." (PMID 37188744, 2023). "Hyperphosphorylation of tau within the brains of Alzheimer’s disease (AD) patients has been associated with a deficiency in insulin signaling within the brains of individuals with type 2 diabetes (DM)." (PMID 38002034, 2023). "Their results showed that IMCL could serve as an additional parameter/biomarker for increased diabetes risk, since it identifies insulin resistance in pGDM patients and also those patients who were diagnosed previously and/or required insulin throughout pregnancy." (PMID 36810530, 2023). "Diabetes mellitus (DM) is a group of physiological abnormalities characterized by hyperglycemia caused by insulin resistance, insufficient insulin production, or overproduction of glucagon." (PMID 37978526, 2023). "Diabetes mellitus (DM) represents a current global epidemic and a complex metabolic disorder characterized by chronic hyperglycemia caused by insulin resistance, impaired insulin secretion, or both." (PMID 37111385, 2023). "Diabetes mellitus (DM) is a chronic metabolic disorder characterized by high glucose levels resulting from insulin deficiency or insulin insensitivity." (PMID 37237992, 2023). "Diabetes mellitus (DM) is a chronic endocrine–metabolic disease characterized by a sustained rise in blood glucose caused by deficient insulin secretion or action and accompanied by changes in nutrient metabolism." (PMID 37933068, 2023). "Insulin resistance (IR) is defined as a reduction in tissue sensitivity to normal plasma insulin levels, which is a prominent feature of the metabolic syndrome (MetS) and type 2 diabetes mellitus (DM), has been implicated in the pathogenesis of AS." (PMID 37660027, 2023). "Therefore, a slow glucose release induced by SDS fraction is accompanied by a low insulin level, which might provide wide health benefits to reduce the risk of diabetes or metabolic syndrome." (PMID 37238882, 2023). "Hyperphosphorylation of tau within the brains of Alzheimer’s disease patients has been associated with a deficiency in insulin signaling within the brains of individuals with type 2 diabetes (DM)." (PMID 38002034, 2023). "Secondary diabetes mellitus (DM) in secretory pheochromocytomas and paragangliomas (PPGLs) is encountered in up to 50% of cases, with its presentation ranging from mild, insulin resistant forms to profound insulin deficiency states, such as diabetic ketoacidosis and hyperglycemic hyperosmolar state." (PMID 37731140, 2023). "Moreover, diabetes treatment associated with insulin use and adolescent weight changes may also increase the incidence of persistent eating problems." (PMID 37710329, 2023).